CRP (C-reactive protein)
Diseases named in the same sentence as CRP in open-access papers (continued):
Sharing a sentence is not in itself a finding about the gene and the disease.
Obesity (continued). "This type of depression is a significant risk factor for weight gain and subsequent obesity and was specifically associated with increased peripheral levels of inflammatory markers, such as C-reactive protein (CRP)." (PMID 33731235, 2021). "Our aims were to elucidate the relationships between pre-surgery high sensitivity-CRP (hs-CRP) values and post-surgery weight loss and liver steatosis and fibrosis in patients with severe obesity undergoing Roux-en-Y gastric bypass." (PMID 33919641, 2021). "The association between obesity and elevated serum CRP levels has been well explained by pathophysiological mechanisms." (PMID 34923973, 2021). "Obesity is a systemic inflammatory pathological state associated with increased levels of numerous inflammatory markers including C-reactive protein (CRP), IL-6, TNF-α, and some adipokines associated with inflammatory factors such as RBP4 or chemerin." (PMID 34035808, 2021). "Obesity is an acknowledged chronic, inflammatory condition, and has been associated with inflammatory indicators including C-reactive protein and white blood cell counts." (PMID 33436068, 2021). "In humans, C-reactive protein is an inflammatory marker linked to obesity and atherosclerosis, and more recently also to NAFLD." (PMID 35052573, 2021). "Similar to other studies, this study population reported a significant association between overweight/obesity and elevated CRP levels." (PMID 33680494, 2021). "On the other hand, these metabolic parameters were significantly associated with disease duration, CV history, CRP, obesity, PWV, and IMT." (PMID 34680168, 2021). "Despite the short duration of this intervention, there is an outstanding reduction in the obesity scores and a possible reduction in the low-graded persistent inflammation (CRP) associated with this disorder." (PMID 32899955, 2020). "The presence of abnormal HDL-C, HOMA-IR, hs-CRP and multiple cardiometabolic risk factors were more common among youth with severe obesity." (PMID 32522176, 2020). "We found that, similar to normal aging, obesity is associated with significantly higher levels of CRP, PGE2, monocytes and granulocytes and significant reductions in NK cells." (PMID 32027700, 2020). "Our present study utilized cross-sectional data from KNHANES to investigate the association of obesity and central obesity with elevated hs-CRP levels." (PMID 33182500, 2020). "In the present study, plasma levels of IL-6 and CRP were increased before the intervention, reflecting obesity-associated chronic low-grade inflammation at baseline, and significantly declined following lifestyle-induced weight loss." (PMID 33082492, 2020). "More specifically, for women, having the last child before age 25 was associated with a higher level of CRP (B = 0.239, p < .05), a higher cholesterol ratio (B = 0.136, p < .05), and higher risk of obesity (OR = 1.334, CI = [1.01, 1.77])." (PMID 32133595, 2020). "Obesity has been associated with circulating inflammatory biomarkers, including higher concentrations of leptin, C-reactive protein (CRP), interleukin (IL)-6, and tumor necrosis factor-α (TNFα), and lower adiponectin." (PMID 33259491, 2020). "Obesity is associated with chronic low-grade inflammation, and markers of inflammation such as CRP, TNF-α, and IL-6 have been reported to correlate positively with adipocyte size." (PMID 33178661, 2020). "Even though obesity is known to be associated with the elevation of CRP, our subjects whose BMIs were between 25 and 30 kg/m2 (Asian obesity criteria is BMI 25 and higher) showed normal CRP levels." (PMID 32824387, 2020). "The scientific literature has shown that obesity is associated with high levels of CRP because the secretion of inflammatory cytokines is increased in individuals affected by obesity." (PMID 32994872, 2020). "When excluding acute infections, CRP has been shown to be elevated in children with obesity, to be associated with hyperlipidemia and to predict IR." (PMID 32154197, 2020).
Obesity (continued). "Recent research has shown that weight loss as a result of bariatric surgery is an effective method to decrease obesity-associated CRP levels." (PMID 32326591, 2020). "In human, CRP is consistently the strongest factor associated with overweight and obesity as revealed by large epidemiological studies." (PMID 32154244, 2020). "Inflammatory biomarkers that are thought to be associated with obesity include C-reactive protein (CRP), fibrinogen, uric acid, and gamma-glutamyltransferase (GGT)." (PMID 32879892, 2020). "Obesity and inflammation expand and mobilize MDSCs and their precursors via molecules such as IL-6, CRP, IL-1β, and leptin, increasing their susceptibility to tumor-derived signals that further drive their recruitment and suppressive capacity." (PMID 33123173, 2020). "Evidence in different clinical inflammatory conditions, including polycystic ovary syndrome, psoriasis, hidradenitis suppurativa, and obesity, showed a strong association between PhA and inflammatory markers, including hs-CRP levels." (PMID 32664600, 2020). "Obesity is associated with a chronic state of low-grade inflammation presenting increased levels of inflammatory markers, such as C-reactive protein (CRP) and pro-inflammatory cytokines." (PMID 32555994, 2020). "It is known that the concentration of CRP in the peripheral circulation is associated with high BMI and other obesity markers." (PMID 32106828, 2020). "This study aims to examine the association of educational attainment, C-reactive protein, and obesity among Black women in the USA." (PMID 31728932, 2020). "Slightly elevated levels of C-reactive protein (CRP) represent a surrogate parameter of a systemic low-level inflammation in obesity and have been associated with atherosclerosis, metaflammation, and increasing body fat percentage." (PMID 32154197, 2020). "In other words, obesity was associated with the levels of CRP and IL-6 independently of OSAS severity and sex." (PMID 32629899, 2020). "Obesity has been associated with markers of chronic inflammation, such as levels of C-reactive protein, tumour necrosis factor α, amyloid A and interleukin−6, as well as white blood cell counts." (PMID 32512798, 2020). "The uncertain associations between CRP and comorbidity observed in other studies in subjects with obesity seem to imply also to those with morbid obesity." (PMID 32646381, 2020). "Conservative treatment of obesity has been shown to reduce BMI-SDS, IR, and CRP in other programs, but the association and development of BMI, IR, inflammation, and adipokines in the treatment of obesity are not fully understood." (PMID 32154197, 2020). "As an acute-phase reactant to inflammation and infection, C-reactive protein (CRP) has been found to be the strongest factor associated with obesity." (PMID 32154244, 2020). "Female individuals consistently exhibited a higher risk of elevated hs-CRP levels for both measures of obesity than men, both individually and combined." (PMID 33182500, 2020). "We have found that the variation of the increased indices of inflammation such as CRP highly inversely associates with IGF-1 in obesity." (PMID 32806629, 2020). "C-reactive protein (CRP) level in obesity patients is significantly increased and associated with the occurrence and progression of cardiovascular disease." (PMID 32046736, 2020). "Obesity and insulin resistance are associated with increased CRP, increased citrulline and decreased arginine bioavailability in Teens." (PMID 33079935, 2020). "One study with a very small sample size was identified from the Sudan, where researchers found a strong association between CRP levels and obesity." (PMID 33141863, 2020). "These MRI results clearly showed that the observed higher body weight caused by long-term chronic CRP elevation was due to high fat volume, validating the existence of obesity in these animals." (PMID 32154244, 2020).
Obesity (continued). "Surprisingly, CRP showed a positive correlation with BMI in female subjects only, with previous studies observing a markedly stronger association between CRP and obesity in women than in men26." (PMID 32994460, 2020). "Factors such as age, smoking and obesity have been associated with alterations of the levels of CRP." (PMID 32994872, 2020). "Increased plasma levels of CRP (p < 10 − 5), insulin (p < 10 − 4), and leptin (p < 10 − 7) showed dysmetabolic disorders associated with overweight/obesity." (PMID 32454823, 2020). "We measured plasma CRP, as a clinically-relevant marker of inflammation, which predicts future disease risk, and used BMI as a proxy for obesity and future metabolic risk." (PMID 31164901, 2019). "We further analyzed the association of CRP and 8-isoprostane with the obesity measures and other inflammatory, oxidative stress, and endothelial dysfunction markers." (PMID 31737180, 2019). "Obesity itself is associated with increases in the levels of various systemic proinflammatory mediators, such as C-reactive protein (CRP), leptin, and interleukin (IL)−68–10." (PMID 31133649, 2019). "In fact, obesity has been associated with elevated levels of proinflammatory markers such as interleukins, C reactive protein (CRP), interferon (IFN)-γ, and tumor necrosis factor (TNF)-α." (PMID 31137906, 2019). "The principle of this statement is that low-grade inflammation caused by CRP and IL-6 mediates obesity, inflammation, insulin resistance and cardiovascular diseases." (PMID 30624536, 2019). "Age, sex, stroke severity, hypertension, AF, obesity, and elevated CRP level were associated with an increased risk of recurrence, while alcohol consumption decreased this risk." (PMID 30808986, 2019). "Most findings in the literature are consistent regarding the association of obesity and higher levels of IL-6 and CRP, corroborating our results." (PMID 31071114, 2019). "High BMI, body fat and fat percentage was associated with high CRP, supporting previous studies linking obesity with increased systemic inflammation." (PMID 31333751, 2019). "And CRP and its combination with obesity and hypertension were associated with increased risk of T2DM." (PMID 30872696, 2019). "CRP was significantly (p < 0.0001) associated with all the three obesity measures such as BMI z-score (r = 0.528), WC z-score (r = 0.523), and WHtR z-score (r = 0.470)." (PMID 31737180, 2019). "A few studies have shown that obesity in pregnancy is linked to risk of obesity and low-grade systemic inflammation in their children, proposing this as the mechanism responsible for our observation of hs-CRP correlation from mother to child." (PMID 30816254, 2019). "Regarding the relationship between obesity and the inflammatory and iron markers, pgBMI was positively associated to IL-6, leptin, and CRP." (PMID 30909605, 2019). "In our cohort, some of the obesity-related genes were associated with leptin, an adipocytokine; CRP, an inflammatory marker; and FMD%, an index of endothelial function." (PMID 31466225, 2019). "Obesity and the metabolic syndrome are accompanied by a ‘low grade’ chronic inflammation, indicated by a well-characterized positive association between obesity indices and inflammatory markers, such as C reactive protein (CRP) and IL-6." (PMID 30639417, 2019). "We concluded that obesity is the main exposure positively associated with IL-6 and CRP and inversely associated with adiponectin (mainly in females)." (PMID 31071114, 2019). "Chronic inflammation with elevated levels of CRP has been associated with obesity, hypertension, heavy drinking, smoking, and low physical activity." (PMID 30872696, 2019). "Evidence for a genetic influence on the relationship between immune factors, metabolic syndrome and cardiovascular risk factors is provided by the association of alleles increasing CRP levels and increased risk of obesity." (PMID 31622379, 2019).
Obesity (continued). "The results of this study indicate that among individuals with overweight or obesity, higher phytate intakes is associated with lower odds of elevated CRP concentration." (PMID 31052485, 2019). "The types of food consumed, including ultra-processed products, strongly influence obesity, and are also associated with higher serum CRP levels." (PMID 31314878, 2019). "The types of food consumed, including ultra-processed products, strongly influence obesity 9,10,11,12 and are also associated with higher serum CRP levels." (PMID 31314878, 2019). "We found that both obesity and hypertension interact with the association between CRP and incident T2DM." (PMID 30872696, 2019). "This study focuses on individuals with overweight and obesity because obesity is associated with low grade chronic inflammation marked by increased production of adipocyte cytokines, leading to an increase in hepatic CRP production." (PMID 31052485, 2019). "Increased CRP and treatment resistance were also associated with other aspects of clinical heterogeneity in depression including obesity, vegetative symptoms of fatigue and sleep disturbance, state anxiety and a history of childhood adversity." (PMID 29764522, 2019). "Although both were associated with salivary CRP, insulin, and adiponectin, leptin was unique for obesity evaluated by waist circumference." (PMID 31236292, 2019). "We considered the blood levels of IL-6 and hs-CRP as inflammatory markers implicated in obesity and metabolic disorders." (PMID 31440209, 2019). "CVD risk factors such as overweight/obesity, dyslipidemia, hypercholesterolemia, and elevated CRP are associated with endothelial dysfunction." (PMID 29476238, 2019). "Because it has been reported that calcium intake is associated with reduced obesity and obesity is positively associated with hs-CRP levels, we further adjusted for BMI, with similar results (Model 3: p for trend = 0.008)." (PMID 29371759, 2018). "Previous study showed that PPAR polymorphisms were independently associated with CRP levels in Chinese Han population; PPARs polymorphisms interact with overweight/obesity to set CRP levels." (PMID 29849618, 2018). "The western dietary pattern, obesity, high body fat, high waist or hip circumference, and high waist-to-hip ratio were significantly associated with increased odds ratios of high CRP and NLR in both genders." (PMID 30454030, 2018). "A similar inverse but stronger association of CRP and telomere length was reported recently in relation to cardiovascular disease risk and obesity." (PMID 29486769, 2018). "Age (HR = 1.036 95% CI 1.020 to 1.053) and CRP levels (HR = 1.123 95% CI 1.077 to 1.171) were a significant risk factor for mortality while obesity (HR = 0.499 95% CI 0.305 to 0.817) showed a protective effect." (PMID 29464097, 2018). "A positive association between DNA damage and serum CRP-hs concentration was found and a stronger correlation was observed among obese women than in the controls, suggesting an impact of obesity-associated inflammation." (PMID 29738492, 2018). "We also test for interactive effects, which would indicate that the association between obesity and high sensitivity CRP (hsCRP) is modified among individuals who report being lonely (and vice versa)." (PMID 30439985, 2018). "Our study indicated that the cardiovascular risk factors including obesity, pre-hypertension, dyslipidemia, and high hs-CRP were common in studied women." (PMID 30479987, 2018). "CRP is produced in the liver on the binding of proinflammatory cytokines and is associated with obesity." (PMID 29849871, 2018). "Increased levels of the C-DII are associated with an increase in levels of CRP which is a risk factor for obesity and chronic disease." (PMID 30061487, 2018). "The association between CRP and vitamin A, for example, has been analyzed in children with an infectious disease, night blindness or obesity." (PMID 30205424, 2018).
Obesity (continued). "CRP is a commonly used biomarker in the study of depression and obesity, and shows positive associations with both disease states." (PMID 30524737, 2018). "Previously, chronic, unresolved inflammation in obesity has been linked to local and systemic production of pro-inflammatory cytokines, particularly C-reactive protein, IL-6, TNF-α, as well as chemotactic and adipokine signaling molecules." (PMID 29738558, 2018). "The aim of this paper was to assess the association of obesity measurements and IL-6, CRP and adiponectin." (PMID 29704817, 2018). "Other studies have shown association between obesity, levels of C-reactive protein (CRP), osteopenia/osteoporosis, hypothyroidism, and PAD." (PMID 29858704, 2018). "Obesity was associated with higher basal levels of serum insulin (P < 0.05), plasma triacylglycerol (P < 0.01), plasma cholesterol (P < 0.01), and plasma CRP (P < 0.01), as well as increased insulin resistance determined by HOMA‐IR (P < 0.05)." (PMID 30009507, 2018). "Obesity and loneliness have both been identified as predictors of elevated CRP, which in turn, is a risk factor for CVD and coronary heart disease." (PMID 30439985, 2018). "This study found depression to be associated with later CRP levels, the relationship was stronger for cumulative episodes of depression, and the association persisted after controlling for obesity, smoking and medication use." (PMID 30460320, 2018). "An increase in plasma levels of inflammatory markers and acute phase proteins such as C-reactive protein (CRP) is observed in subjects with obesity and associated diseases." (PMID 29910808, 2018). "Obesity and an HF diet are associated with low-grade chronic inflammation in many tissues, which is confirmed by increased plasma concentrations of CRP, tumor necrosis factor α (TNF-α), and interleukins." (PMID 29849871, 2018). "And like obesity, loneliness (and similar social constructs including social isolation) is associated with elevated CRP." (PMID 30439985, 2018). "Association between ‘elevated’ and ‘clinically raised’ CRP and physical unhealthy days remained significant even after adjustment for obesity or inflammation-modulating covariates (OR = 1.36, 95% CI: 1.02–1.82, and OR = 1.75, 95% CI: 1.21–2.54, respectively)." (PMID 30123515, 2018). "Obesity and loneliness are associated with C-reactive protein (CRP), a predictor of cardiovascular disease." (PMID 30439985, 2018). "It is also important to note that their results are further confounded by the populations studied, given that both CRP and adipocytokines are affected by obesity and weight loss." (PMID 29361967, 2018). "In that study, which motivated the present one, CK and lean body mass were negatively associated with CRP indicating an inhibitory effect on obesity-related inflammation by CK and/or by other muscular metabolites." (PMID 29813131, 2018). "There is also some evidence suggesting a positive association between obesity and immunoglobulin levels, including a study which reported concomitant elevations of anti-food IgG and CRP in obese compared to normal weight juveniles." (PMID 28725447, 2017). "LAR has also been found to be related to low grade inflammation and insulin resistance independently of obesity, with a more powerful association with CRP and HOMA-IR than leptin or adiponectin alone." (PMID 28878827, 2017). "Obesity is a major factor associated with elevated CRP in individuals with the metabolic syndrome, and CRP decreases after weight loss in obese subjects." (PMID 28404960, 2017). "Uric acid and high us-CRP are risk factors for the onset of type 2 DM and obesity 39, and high levels of these factors can identify individuals with an inflammatory condition." (PMID 28492722, 2017).